AHI1 (Abelson helper integration site 1)
Diseases named in the same sentence as AHI1 in open-access papers (continued):
Sharing a sentence is not in itself a finding about the gene and the disease.
Joubert Syndrome type 3 (5 papers, 2021 to 2024). "AHI1 is implicated in ciliary protein transport and immune dysregulation, with rare variation in this gene contributing to Joubert syndrome type 3." (PMID 37547536, 2023). "In one patient, two missense variants in the AHI1 gene (NM_017651.5, NP_060121.3) were indicated as the most probable causative variants (c.1828C>T p.Arg610Ter and c.1829G>C p.Arg610Pro), indicating a possible genetic diagnosis of Joubert Syndrome type 3." (PMID 39202371, 2024). "We identified two frameshift variants in the AHI1 and TMEM237 genes, leading to Joubert syndrome types 3 and 14, respectively." (PMID 38570878, 2024). "CLN3 and AHI1 typically cause JNCL 3 and Joubert syndrome 3, respectively; however, probands of families IRD16 and IRD49 showed typical RP phenotypes, without any additional syndromic manifestations of either disease, at least for their current age." (PMID 33921607, 2021).
Anxiety (4 papers, 2018 to 2021). Intense feelings of nervousness, tension, or panic often arise in response to interpersonal stresses. "The behavioral phenotype of Ahi1+/− mice and their altered brain connectivity suggest that Ahi1 deficiency during neurodevelopment could attenuate the effect of environmental cues that normally evoke stress and anxiety." (PMID 29967406, 2018). "While the anxiety level was normal in mice with AHI1 knockdown in layer 2/3 pyramidal neurons of the PFC, it was decreased in AHI1 heterozygous knockout mice." (PMID 33046712, 2020). "In the current study we replicated our findings regarding lower levels of anxiety in stress-naïve Ahi1+/− compared to Ahi1+/+ mice in the OF, light-dark box and EPM." (PMID 29967406, 2018). "We had previously shown that Ahi1+/− mice not subjected to prior stress, displayed significantly lower anxiety levels than wild type Ahi1+/+ mice on a number of anxiety tests as well as functional corticolimbic disconnectivity." (PMID 29967406, 2018). "Previous studies of mice heterozygous for Ahi1 knockout (Ahi1+/−) revealed an attenuated anxiety response on various relevant paradigms, in the context of a normal glucocorticoid response to caffeine and pentylenetetrazole." (PMID 29967406, 2018). "However, heterozygous Ahi1 knockout (Ahi1+/−) mice revealed an attenuated anxiety response on various relevant paradigms and were found to be hyposensitive to stress." (PMID 33782379, 2021). "AHI1 knockdown caused decreased depressive behavior, but did not alter exploratory behavior, anxiety, locomotor activity, and working memory." (PMID 33046712, 2020). "It is therefore likely that the increased social interaction in AHI1 heterozygous knockout mice may result at least partly from the reduced anxiety level." (PMID 33046712, 2020). "Notwithstanding the discrepant nature of our findings regarding the effects of CUS on anxiety and neurogenesis, our central hypothesis regarding stress hyporesponsiveness in Ahi1+/− mice was supported by the results of our study." (PMID 29967406, 2018). "However, extensive behavioral phenotyping of Ahi1+/− mice demonstrated decreased anxiety and glucocorticoid response to stressful stimuli on several behavioral tests." (PMID 29967406, 2018). "The similarity of the anxiety profile of Ahi1+/+ mice that underwent CUS to the phenotype of Ahi1 deficient mice suggests that chronic stress and Ahi1 deficiency may share a mechanism affecting brain anxiety circuits, such as reduction in amygdalar CRH level." (PMID 29967406, 2018). "Post hoc comparisons of simple main effects with Bonferroni correction revealed that CUS-exposed Ahi1+/+ mice spent longer in the open area of the arena than Ahi1+/+ controls (p < 0.05), suggesting that the CUS protocol decreased the anxiety of these mice." (PMID 29967406, 2018). "Thus, the low anxiety profile of Ahi1+/− mice could ostensibly reflect stress resilience while it actually derives from a cognitive-emotional deficit that may have relevance to the pathogenesis of neuropsychiatric disorders in which the gene has been implicated." (PMID 29967406, 2018). "Our current findings show that exposure to CUS induced decreased sucrose preference, reduced anxiety (manifested on three anxiety tests—open field, light-dark box, EPM) and decreased response to acute stress manifested on FC and SIH tests in Ahi1+/+ mice." (PMID 29967406, 2018). "Consistent with the other anxiety tests performed in this study, Ahi1+/− mice spent longer in the open arms of the EPM, suggesting reduced anxiety of these mice." (PMID 29967406, 2018). "Most notable among these is the fact that contrary to the majority of reported findings, we observed reduced rather than increased anxiety in wild type Ahi1+/+ mice exposed to CUS and also increased rather than reduced hippocampal neurogenesis." (PMID 29967406, 2018).
Anxiety (continued). "We hypothesized that CUS would induce anhedonia in Ahi1+/+ mice with alterations in neurogenesis and would not affect anxiety, whereas Ahi1+/− mice that were previously characterized as hyporesponsive on exposure to acute stress, would be less affected or even indifferent to the CUS protocol." (PMID 29967406, 2018). "In Ahi1+/− mice, CUS did not affect anxiety measures on the open field, light-dark box or EPM." (PMID 29967406, 2018).
asthma (3 papers, 2020 to 2023). "Additionally, the identified childhood-onset asthma-associated gene of JAZF1 has evidence of genetic interactions with identified genes of AHI1, NSMCE1, TDRKH, CD52, and HLA-DRB1 based on a genome-wide map of genetic interaction inferred from radiation hybrid genotypes." (PMID 32867763, 2020). "For example, among the strongest associations with the lead SNPs at the following loci include: CLEC16A, CD28, MICA, and ELMO1 with eosinophil counts; AHI1 with monocyte and neutrophil counts, asthma, and hay fever (also shared by CD28); and MICA with type 1 diabetes." (PMID 37120605, 2023).
retinitis pigmentosa (3 papers, 2019 to 2021). Retinitis pigmentosa (RP) is an inherited retinal dystrophy leading to progressive loss of the photoreceptors and retinal pigment epithelium and resulting in blindness usually after several decades. "Missense mutations in the WD40 domain of the AHI1 gene can underlie non-syndromic retinitis pigmentosa." (PMID 33732702, 2021). "Thus, we suspect that the phenotype of patient A1 with retinitis pigmentosa may be a result of variations in both ABCA4 and AHI1 genes, which highlights the genotypic variability associated with ABCA4-related retinitis pigmentosa." (PMID 33732702, 2021).
Ataxia (2 papers, 2016 to 2023). Ataxia refers to impaired coordination of voluntary muscle movement. "For example, AHI1, as one of them, has been demonstrated that its mutations can result in JBTS, a human disease characterized by psychomotor delay, cerebellar hypoplasia, consecutive ataxia, and so on32." (PMID 27991561, 2016).
autoimmune disease (2 papers, 2016 to 2023). A disorder resulting from loss of function or tissue destruction of an organ or multiple organs, arising from humoral or cellular immune responses of the individual to their own tissue constituents. "Notably, a GWAS in the autoimmune disease multiple sclerosis detected a susceptibility variant in AHI1 (rs4896153) (with LD extending into LINC00271) that was subsequently shown to have strong cis-eQTL effect on overall AHI1 expression." (PMID 37547536, 2023).
bipolar disorder (2 papers, 2017 to 2024). A disorder of the brain that causes unusual shifts in mood, energy, activity levels and the ability to carry out day-to-day tasks. "Hap1 and Ahi1 stabilize each other, and are important for maintaining the level of tyrosine kinase receptor B (TrkB), whose signaling seems to be critical in the risk of depression and bipolar disorder, and pivotal for brain development." (PMID 28125008, 2017). "Our study showed also higher AHI1 expression in the group of euthymic BD patients (regardless of used mood stabilizer) compared to healthy control, which may suggest the role of AHI1 expression in the course of bipolar disorder." (PMID 38036661, 2024). "Potential evidence of the association between some variants of AHI1 and bipolar disorder susceptibility has been reported, but no connections with clinical outcomes were revealed." (PMID 28125008, 2017). "So far, it was not studied if AHI1 may be associated with lithium response in bipolar patients and if its expression correlates with innate immunity changes in bipolar disorder." (PMID 38036661, 2024).
chronic myeloid leukemia (2 papers, 2011 to 2021). "In chronic myeloid leukemia cells, a complex formed by DNM2, Abelson helper integration site-1 (AHI-1) and the fusion oncogene BCR-ABL leads to activation of DNM2 through its phosphorylation by the BCR-ABL tyrosine kinase." (PMID 34294140, 2021).
cutaneous T-cell lymphoma (2 papers, 2011 to 2025). "Abelson helper integration site 1 (AHI1) is regulated at multiple stages of hematopoiesis, with significant dysregulation observed across various human leukemic cell lines, most notably in cutaneous T-cell lymphoma (CTCL) cell lines, where AHI1 transcript levels are elevated by up to 40-fold." (PMID 41300981, 2025).
Hearing impairment (2 papers, 2023). A decreased magnitude of the sensory perception of sound. "We concluded that the POU4F3 variations might regulate Wnt, Notch, and/or BMP pathways, specifically leading to the misregulation of BMP2, MYO6, and AHI1 in the pathogenesis of hearing loss." (PMID 37537203, 2023).
Hydrocephalus (2 papers, 2012 to 2021). Hydrocephalus is an active distension of the ventricular system of the brain resulting from inadequate passage of CSF from its point of production within the cerebral ventricles to its point of absorption into the systemic circulation. "Knock-down of ahi1 in zebrafish caused a curved body and abnormalities in the development of the eye, hindbrain (hydrocephalus) and otoliths, together with defects in cyst formation in the pronephric kidney tubules." (PMID 33917666, 2021). "To date, murine models of Ahi1 and Cep290 knockdown have not demonstrated gross hydrocephalus." (PMID 23028714, 2012).
Joubert syndrome-related disorders (2 papers, 2015 to 2025). "Joubert syndrome-related disorders exhibit clinical heterogeneity due to their various genetic causes, including three genes (CEP290, AHI1/JBTS3, NPHP1/JBTS4) and two loci (JBTS1 and JBTS2)." (PMID 40538625, 2025).
Kidney Cyst (2 papers, 2017 to 2019). Abnormal fluid filled sac within the kidney, either acquired or congenital. "Missense alleles of AHI1 were associated with increased neurological involvement in a small number of CEP290-LCA patients, while morpholino knockdown of cep290 increased the frequency of kidney cysts in cc2d2a-/- mutant zebrafish." (PMID 30970040, 2019). "Distal pronephric duct cilia were absent in mutant fish; however, only 9% of ahi1 mutants had kidney cysts by 5 dpf, suggesting that the pronephros remained largely functional." (PMID 28118669, 2017).
Obesity (2 papers, 2019 to 2024). Accumulation of substantial excess body fat. "AHI1 is required for both cerebellar and cortical development and has been previously shown to be associated with fat development and obesity via regulating insulin signaling." (PMID 31737448, 2019). "Among these genes, AHI1, AKAP9, ANKRD12, CCDC18, IFT74, NEXN, etc., have been shown to play an important role in adipose deposition or obesity." (PMID 38474122, 2024).
dysplasia (1 paper, 2019). A usually neoplastic transformation of the cell, associated with altered architectural tissue patterns. "We injected a morpholino to zebrafish embryos, which can generate mutant Ahi1 lacking the intact WD40 repeats, and found RGC axon misprojection and ocular dysplasia in 4 dpf (days post-fertilization) larvae after the injection." (PMID 30949029, 2019).
glomerular disease (1 paper, 2023). "The AHI1 association, in particular, suggests a link between a ciliary gene and glomerular disease and reinforces an emerging paradigm in nephrology: in genes harboring rare Mendelian variants, common alleles can increase the susceptibility of polygenic diseases." (PMID 37547536, 2023).
Huntington disease (1 paper, 2015). Huntington disease (HD) is a rare neurodegenerative disorder of the central nervous system characterized by unwanted choreatic movements, behavioral and psychiatric disturbances and dementia. "Huntingtin-associated protein a (Hap1) is an intriguing neuronal-enriched protein that interacts with several disease-related proteins, including huntingtin and Ahi1, whose mutations cause Huntington's disease (HD) and Joubert syndrome, respectively." (PMID 25875952, 2015).
mood disorder (1 paper, 2024). A cognitive disorder a disturbance in which the person's mood is hypothesized to be the main underlying feature. "The AHI1 gene is located on the long arm of chromosome 6q23, a region associated with susceptibility to mood disorders." (PMID 38036661, 2024).
multiple sclerosis (1 paper, 2023). A progressive autoimmune disorder affecting the central nervous system resulting in demyelination. "AHI1 has also been shown to be involved in actin organization, and therefore the authors of this study speculated that AHI1 may play a role in the formation or stabilization of the T-cell receptor synapse as a mechanism for its association with multiple sclerosis." (PMID 37547536, 2023).
Nystagmus (1 paper, 2018). Rhythmic, involuntary oscillations of one or both eyes related to abnormality in fixation, conjugate gaze, or vestibular mechanisms. "AHI1 gene mutations are the most frequently correlated with nystagmus." (PMID 30518138, 2018).
psychosis (1 paper, 2010). "There are several reasons to consider AHI1 a candidate gene for psychotic disorders." (PMID 20805890, 2010).
psychiatric disorder (5 papers, 2014 to 2025). A disorder characterized by behavioral and/or psychological abnormalities, often accompanied by physical symptoms. "Our previous study demonstrated that conditional Ahi1 knockout (KO) in mice by a Cre-loxp system causes depressive behaviors, which are common symptoms in human psychiatric diseases." (PMID 24691070, 2014). "The increasing line of evidences indicates that AHI1 is associated with psychiatric diseases." (PMID 24691070, 2014). "We have used mice heterozygous for a constitutional knockout of the Ahi1 gene (Ahi1+/− mice) to conduct translational studies of the Ahi1 gene and to further elucidate the potential role of the gene in psychiatric disorders." (PMID 29967406, 2018). "Moreover, differential expression of genes with a postulated role in the formation of neural projections, such as AHI1, have been implicated in psychiatric disorders such as SCZ, and ASD as well as in modulation of emotional phenotypes and stress vulnerability in relevant Ahi1 knockout mouse models." (PMID 25414627, 2014).
kidney disease (4 papers, 2015 to 2024). "Renal disease consistent with NPHP has also been described in patients with JBTS with AHI1 mutations." (PMID 26541515, 2015).
brain disease (3 papers, 2011 to 2021). "Three genes (AHI1, CSPP1, and TCTN1) in the top 10 of the PSGs associated with human brain diseases, with raw dN/dS > 2, are required for both cortical and cerebellar development in humans." (PMID 33441416, 2021). "Also discussed are potential applications of targeting specific AHI-1 interaction complexes as a new therapeutic strategy for treatment of CML and brain disorders." (PMID 22248740, 2011).
tumor (2 papers, 2011 to 2021). "The downregulated genes GDPD5, NXPH1, and AHI1 were identified as tumor suppressors, while the upregulated genes CPLX3 and SPAG6 were regarded as oncogenes." (PMID 34950701, 2021). "The upregulated genes CPLX3 and SPAG6 appeared to be associated with poor survival, whereas the downregulated genes GDPD5, NXPH1, and AHI1 were identified as tumor suppressors." (PMID 34950701, 2021). "Two strong candidates identified in this study are a tyrosine kinase, HCK, and a tumor suppressor, BIN1, which show upregulation at both RNA and protein levels in AHI-1-suppressed CTCL cells." (PMID 22248740, 2011).
AHI1 also shares sentences with these, for which no sentence is quoted: retinal disease (4 papers); systemic lupus erythematosus (3); acute myeloid leukemia (2); Cognitive impairment (2); dyslexia (2); hay fever (2); Joubert syndrome 3 (2); neurological disease (2); apraxia (1); Atrophy (1); autosomal recessive disease (1); Bardet-Biedl syndrome (1); Batten disease (1); blast crisis (1); chronic kidney disease (1); communication disorder (1); cyst (1); dystroglycanopathies (1); eczema (1); genetic disorder (1); hematologic malignancies (1); hereditary cancer (1); inflammatory bowel disease (1); intellectual disabilities (1); Leber congenital amaurosis (1); Mainzer‐Saldino syndrome (1); metabolic disease (1); metabolic syndrome (1); muscular dystrophy (1); neurodevelopmental disorder (1).
A further 10 diseases each share a sentence with AHI1 in 1 paper.